PTPN11 (protein tyrosine phosphatase non-receptor type 11)
Diseases named in the same sentence as PTPN11 in open-access papers (continued):
Sharing a sentence is not in itself a finding about the gene and the disease.
rheumatoid arthritis (8 papers, 2017 to 2025). A chronic, systemic autoimmune disorder characterized by inflammation in the synovial membranes and articular surfaces. "Recently, Keisuke reported that the Ptpn11 gene is up-regulated in fibroblast-like synoviocytes of rheumatoid arthritis (RA) compared to that of OA." (PMID 33898435, 2021). "The inflammatory targets that mediate rheumatoid arthritis mainly include (TNF, PTPN11, IL6, etc.); the main targets that mediate RA oxidative stress are NOS3; the targets that mediate the destruction of extracellular matrix tissue in RA mainly include (MMP9, MMP2, ANXA5, etc.)." (PMID 38238321, 2024).
scoliosis (8 papers, 2013 to 2024). A congenital or acquired spinal deformity characterized by lateral curvature of the spine. "Scoliosis is a common phenotype in mutant mouse models that disrupt genes involved with the development and homeostasis of cartilages and connective tissues, including Adgrg6/Gpr126, Sox9, Shp2 (Ptpn11), Gdf5/6 and Fgf3." (PMID 31848143, 2019).
acute lymphoblastic leukemia (7 papers, 2016 to 2025). Leukemia with an acute onset, characterized by the presence of lymphoblasts in the bone marrow and the peripheral blood. "Mutations in RAS pathway proteins (e.g., KRAS, NRAS, FLT3, PTPN11, and NF1) are highly prevalent in acute lymphoblastic leukemia (ALL), with such mutations occurring in 40%–50% of pediatric B cell ALL cases." (PMID 35243242, 2022).
atherosclerosis (7 papers, 2018 to 2025). A disease characterized by the build-up of fatty material and calcium deposition in the arterial wall resulting in partial or complete occlusion of the arterial lumen. "Our results indicated that compounds in Tualang honey such as luteolin, fisetin, hesperitin, catechin, and kaempferol may have a crucial impact on atherosclerosis through their effects on key biological targets, including PIK3CA, SRC, P1K3R1, EGFR, PTPN11, and AKT1." (PMID 37174317, 2023). "Considering no direct evidence connecting CD38, PTPN11, NOTCH1, TLR7, and KAT2B with the pathogenesis of MMD, their roles in atherosclerosis may also provide a new perspective and direction for future research on the molecular targeted therapy of MMD." (PMID 36605987, 2022).
atrial septal defect (7 papers, 2018 to 2025). Interauricular communication is a congenital malformation characterized by a communication between the atrial chambers of the heart. "PTPN11 variants were linked to PS and atrial septal defects, SOS1 to multiple cardiopathies, and RAF1 to HCM." (PMID 40332000, 2025). "While the 50% proportion for atrial septal defect for patients with PTPN11 mutations was in line with reported findings, only two of eight patients had PS." (PMID 30784236, 2019). "Four of the eight patients with PTPN11 variants had atrial septal defect." (PMID 30784236, 2019). "Whole exome sequencing revealed that the patient harbored a pathogenic variant of PTPN11 (c.A922G p.N308D), which was unfortunately inherited by her 2.5-year-old daughter who had short stature and atrial septal defect but no hypoproteinemia." (PMID 32054441, 2020). "For example, in the case of atrial septal defect (ASD) and ventricular septal defect (VSD), candidate genes can be counted: NKX2-5, GATA4, TBX20, MYH6, and TBX5, while the pathogenesis of atrioventricular septal defect (AVSD) involves genes, such as PTPN11, KRAS, SOS1, RAF1, and CRELD1." (PMID 34946970, 2021).
chronic myeloid leukemia (7 papers, 2016 to 2022). "Remarkably, phosphatases can influence the response to TKI treatment as reported for PTPN1 (PTP1B), PTPN6 (SHP1) and PTPRC (CD45) for BCR-ABL TKIs treatment in chronic myeloid leukemia or for PTPN11 (SHP2) for acquired resistance to ALK-TKIs in ALK-rearranged non-small cell lung cancer (NSCLC)." (PMID 36698412, 2022).
Cognitive impairment (7 papers, 2017 to 2024). Abnormal cognition is characterized by deficits in thinking, reasoning, or remembering. "In summary Ptpn11D61Y mice displayed lower exploratory activity and reduced memory specificity, which is in line with a causal role of disturbed neuronal Ptpn11 signaling in the development of NS-linked cognitive deficits." (PMID 28346493, 2017). "In line with intellectual impairments, similar disabilities were found in the adaptive and behavioral functioning in very small samples of patients with variants of RAF1, compared with patients with variants in PTPN11 or SOS1." (PMID 36012976, 2022). "IQs were significantly lower in patients with variants in PTPN11, KRAS, RAF1, and SHOC2, but no specific cognitive impairments were found." (PMID 36012976, 2022).
gastric atrophy (7 papers, 2009 to 2024). "A three-way interaction between PGC rs4711690 CG/GG, PGC rs6912200 CT/TT, and PTPN11 rs12229892 GA/AA was significantly associated with atrophic gastritis risk (P value for interaction = 0.048, interaction index = 2.82)." (PMID 26158864, 2015). "A study has also reported that a PTPN11 genetic variant increased the risk for gastric atrophy and cancer among CagA positive H. pylori infected people." (PMID 22383989, 2012). "A further study is required to confirm associations of the PTPN11 rs12423190 polymorphism with gastric atrophy in diverse ethnic populations." (PMID 22788847, 2012). "This study revealed that rs2301756 in the PTPN11 gene encoding SHP-2 increased the risk of severe gastric atrophy in H. pylori infected subjects in Japan." (PMID 19589142, 2009). "This study revealed that those who harbor A allele of the PTPN11 rs2301756 polymorphism at intron 3 had a significantly lower risk of severe gastric atrophy." (PMID 19589142, 2009). "Although the significant association was limited only to severe gastric atrophy, this study partially supported the roles of this PTPN11 polymorphism in the gastric atrophy development." (PMID 19589142, 2009). "Genetic factors, such as PTPN11 polymorphisms may contribute to gastric atrophy, through affecting the connection of Cag A and SHP-2 protein." (PMID 22788847, 2012). "Interactions between the HP cagA protein and SHP-2 in gastric epithelial cells are believed to contribute to the development of GC The PTPN11 AA genotype was associated with reduced risk of gastric atrophy in a Japanese population of HP seropositive individuals." (PMID 19822020, 2009). "Although the G allele of PTPN11 may be a part of the genetic traits to develop gastric atrophy via signal transduction from CagA, there seems to be other genetic traits involved in this process." (PMID 19589142, 2009). "The interaction effect on atrophic gastritis risk between PGC rs6912200 and PTPN11 rs12229892 (OR = 0.60) was greater than the main effect of a single polymorphism, PGC rs4711690 (OR = 0.78) that was identified in our previous study." (PMID 26158864, 2015). "PTPN11 rs2301756 genotype distribution according to H. pylori seropositivity and the grade of gastric atrophy." (PMID 19589142, 2009).
laryngeal carcinoma (7 papers, 2015 to 2024). Carcinoma that arises from the laryngeal epithelium. "PTPN11 also promotes laryngeal cancer growth through the Ras/Raf/Mek/Erk pathway and serves as a prognostic indicator for laryngeal cancer." (PMID 35957898, 2022).
lymphedema (7 papers, 2012 to 2025). Excess fluid collection in tissues, causing swelling. "Postnatally, the prevalence of lymphedema differs from 16% in patients with pathogenic PTPN11 variants to 44% in patients with pathogenic SOS1 variants, and the prevalence of acquired chylothorax is 4% in patients with pathogenic RIT1 variants." (PMID 39229301, 2024). "Functional mutations in CBL and PTPN11 can cause NS with lymphedema." (PMID 40766782, 2025). "Primary lymphedema can be an indicator of various complex hereditary syndromes, such as Noonan syndrome (associated with the PTPN11 gene), lymphedema–distichiasis syndrome (FOXC2), and hypotrichosis–lymphedema–telangiectasia syndrome (SOX18)." (PMID 38791500, 2024). "Only a few hereditary lymphedema-associated gene loci, e.g. VEGFR3, ITGA9 and PTPN11, were detected in human fetuses with this condition; these cases had a poorer prognosis, due to defective lymphangiogenesis." (PMID 22529953, 2012).
myeloid malignancies (7 papers, 2019 to 2025). "Indeed, at least one pathogenic mutation (WT1, FLT3-ITD, IDH2 or PTPN11 mutation) has been identified in all the reported myeloid tumors harboring NPM1::MLF1." (PMID 39443736, 2024). "Of the two tumors with dual FGFR1 + PIK3R1 mutations, one contained an accompanying PTPN11 mutation (p.A72T), which is a known mutational hotspot in myeloid neoplasms thus providing support for pathogenicity [Catalog of Somatic Mutations in Cancer database v91 release]." (PMID 32859279, 2020). "The co-occurrence of U2AF1 and signaling gene mutations also differed across myeloid neoplasms, with NRAS and FLT3 mutations being more common with S34 mutations and CBL, PTPN11 and CSF3R mutations more common with R156/Q157 mutations." (PMID 40386435, 2025).
osteoarthritis (7 papers, 2017 to 2025). A noninflammatory degenerative joint disease occurring chiefly in older persons, characterized by degeneration of the articular cartilage, hypertrophy of bone at the margins and changes in the synovial membrane. "Additionally, the PTPN11 gene is significantly overexpressed in RA fibroblast-like synoviocytes (FLS) compared with osteoarthritis (OA) FLS, suggesting a novel role for SHP-2 in promoting RA FLS invasiveness." (PMID 28854271, 2017).
pancreatic ductal adenocarcinoma (7 papers, 2020 to 2024). An infiltrating adenocarcinoma that arises from the epithelial cells of the pancreas. "For example, through binding with PRPF19 and PTPN11, LINC00673 strengthens the PRPF19–PTPN11 interaction, contributing to enhance PRPF19‐mediated ubiquitination and degradation of PTPN11 in pancreatic ductal adenocarcinoma." (PMID 34337858, 2021).
chronic myelomonocytic leukemia (6 papers, 2011 to 2024). A myelodysplastic/myeloproliferative neoplasm which is characterized by persistent monocytosis, absence of a Philadelphia chromosome and BCR/ABL fusion gene, fewer than 20 percent blasts in the bone marrow and blood, myelodysplasia, and absence of PDGFRA or PDGFRB rearrangement. "After an extensive workup, he was diagnosed with AML/CMML (chronic myelomonocytic leukemia) with a normal karyotype with DNMT3A, CBFB, and PTPN11 mutations." (PMID 35656122, 2022). "In contrast, PTPN11 mutations occur rarely in adult patients with MDS, AML, or chronic myelomonocytic leukemia (CMML)." (PMID 21799948, 2011).
Chylothorax (6 papers, 2022 to 2025). The presence of chyle in the thoracic cavity. "We report the case of a preterm infant with congenital pulmonary lymphangiectasis, chylothorax and hypoxic respiratory failure refractory to conventional management, who was treated with trametinib after identification of a NS PTPN11 class 5 variant." (PMID 40041314, 2025). "The p.Phe285Ser variant is one of the most common mutation at position 285 in the PTPN11 gene and has been associated with NS patients with chylothorax." (PMID 39594917, 2024). "A term female infant with NS (PTPN11) presented with a right-sided unilateral chylothorax, requiring thoracic drainage." (PMID 40835771, 2025). "A preterm female infant with a prenatal diagnosis of NS (PTPN11) presented postnatally with congenital chylothorax." (PMID 40835771, 2025).
cutaneous melanoma (6 papers, 2016 to 2025). A primary melanoma arising from atypical melanocytes in the skin. "We also compared PTPN11 mRNA level between primary and metastatic melanoma samples in the skin cutaneous melanoma dataset in the TCGA database." (PMID 27650545, 2016). "Indeed, mutations in other RAS pathway genes, such as the upstream regulators SOS1, SOS2, GRB2 and PTPN11 (also known as SHP2) and in genes encoding downstream effectors MEK1/2 and ERK1/2, can be detected in ≤5% of cutaneous melanomas." (PMID 35234863, 2022). "PTPN11 mRNA level in cutaneous melanoma appeared higher than that in normal skin although without statistical significance (p = 0.0558), probably due to the small sample size for normal skin tissue." (PMID 27650545, 2016).
Hypertension (6 papers, 2011 to 2025). The presence of chronic increased pressure in the systemic arterial system. "Mutations in the PTPN11 gene can lead to the rough hair, sparse eyebrows, skin keratinization, and obvious hypertension." (PMID 35613128, 2022). "Examining the associations between individual urate genetic risk loci and the related disease outcomes highlighted two loci, GCKR and PTPN11/ATXN2, which drive their association with hypercholesterolemia, hypertension, and ischemic heart disease." (PMID 31626644, 2019).
Ollier disease (6 papers, 2010 to 2024). A rare primary bone dysplasia disorder characterized by the development of multiple mainly unilateral or asymmetrically distributed enchondromas throughout the metaphyses of the long bones. "We next sequenced PTPN11 in DNA samples from 54 patients with the multiple enchondromatosis disorders Ollier disease or Maffucci syndrome, but found no coding sequence PTPN11 mutations." (PMID 21533187, 2011). "Our results suggest that PTPN11 and other members of the RAS/MAPK pathway should be examined in related and as yet unexplained Mendelian phenotypes such as Ollier's disease, Mafucci syndrome (OMIM 166000) and the trichorhinophalangeal syndrome type II (OMIM150230)." (PMID 20577567, 2010).
Splenomegaly (6 papers, 2014 to 2025). Abnormal increased size of the spleen. "Given the persistence of splenomegaly, absolute monocyte counts of 2280/mmc, 9% blasts, PTPN11 mutation, monosomy 7, circulating myeloid precursors, and WBC 16,300/mmc, a diagnosis of JMML was made, and bone marrow transplant was considered as the treatment of choice." (PMID 39336782, 2024).
ulcerative colitis (6 papers, 2017 to 2025). An inflammatory bowel disease involving the mucosal surface of the large intestine and rectum. "Two SNPs in the PTPN11 gene have been related to increased susceptibility to ulcerative colitis (UC) in the Japanese population, but the phenotype of SHP2 remains to be determined." (PMID 31297117, 2019). "Moreover, studies have already demonstrated that PTPN11 gene variants are closely associated ulcerative colitis (UC) but not Crohn’s disease (CD)." (PMID 36212153, 2022).
anemia (5 papers, 2014 to 2024). A reduction in the number of red blood cells, the amount of hemoglobin, and/or the volume of packed red blood cells. "Although anemia is a feature of global SHP2 gain-of-function expression in murine hematopoietic cells, the pleiotropic effects of mutant Ptpn11 alleles on different hematopoietic cell lineages complicate the elucidation of their cell-autonomous roles in the erythropoiesis." (PMID 25289670, 2014).
Autoimmunity (5 papers, 2015 to 2025). The occurrence of an immune reaction against the organism's own cells or tissues. "Given that NK cells and NF-κB are important components of the immune system, gain-of-function mutations of PTPN11 might play a role in the development of autoimmunity." (PMID 32973676, 2020).
hearing loss (5 papers, 2022 to 2024). "Patients with a pathogenic PTPN11 mutation exhibit congenital sensorineural hearing loss." (PMID 37736859, 2023). "Our findings highlight that NS1 with no-to-mild symptoms, other than hearing loss, can be categorized as non-syndromic hearing loss in certain cases; hence PTPN11 may be a much more frequent cause of hearing loss than previously recognized." (PMID 35248088, 2022).
histiocytic sarcoma (5 papers, 2022 to 2025). An aggressive malignant neoplasm with a poor response to therapy, usually presenting as stage III/IV disease. "A study of genomic profiling of primary histiocytic sarcoma suggests the existence of a distinct subtype of primary histiocytic sarcoma characterized by NF1/PTPN11 alterations with predilection for the gastrointestinal tract." (PMID 39998733, 2025). "In dogs, our team was the first to report MAPK pathway activating mutations in PTPN11 gene encoding the protein SHP2, and KRAS in histiocytic sarcomas." (PMID 39202410, 2024). "Recent studies propose a molecular subclassification of histiocytic sarcoma based on the detection or lack of NF1/PTPN11 mutations." (PMID 40901224, 2025). "In the current study, we report our findings of extensive variation in a mutational hotspot region of exon 3 of PTPN11 in canine HS, including the frequency of mutations in PTPN11/SHP2 and KRAS in canine hemophagocytic histiocytic sarcoma (HHS)." (PMID 39202410, 2024).
myocardial infarction (5 papers, 2011 to 2024). Gross necrosis of the myocardium, as a result of interruption of the blood supply to the area, as in coronary thrombosis. "In addition, genetic loci associated with platelet counts, SH2B3–ATXN2 and PTPN11, have been reported to be associated with coronary artery disease (CAD) and myocardial infarction (MI) suggesting a possible role for platelets as an intermediate phenotype." (PMID 21738486, 2011).
pilocytic astrocytoma (5 papers, 2015 to 2020). Pilocytic astrocytoma is a rare subtype of low-grade glioma of the central nervous system characterized by a well circumscribed, often cystic, brain tumor with a discrete mural nodule and long, hair-like projections that extend from the neoplastic astrocytes. "Further analyses of these samples by additional NGS panels revealed KIAA1549–BRAF fusion in six pilocytic astrocytomas and one PTPN11 mutation in the glioneuronal tumor." (PMID 31167453, 2019). "Thus, a case report, revealing a patient with both PTPN11 mutation-associated NS and a pilocytic astrocytoma, is incredibly unique." (PMID 26525348, 2015). "This suggests that PTPN11, which is expressed higher in pilocytic astrocytomas compared to normal tissue, may play a role in FGFR1-mutant tumors." (PMID 26525348, 2015). "The relationship between PTPN11, increased RAS/MAPK activation, and brain tumors is complex; presented here is an interesting case of pilocytic astrocytoma that elucidates the intricacies of tumor growth." (PMID 26525348, 2015). "Additionally, DNT and pilocytic astrocytoma are characterized by either kinase domain tandem duplication or hotspot missense mutations, occasionally with accompanying NF1 or PTPN11 mutation, but lacking the accompanying PIK3CA or PIK3R1 mutation that characterizes RGNT." (PMID 32859279, 2020).
renal cell carcinoma (5 papers, 2017 to 2025). "MiR-124 and miR-489 inhibited the progression of renal cell carcinoma and hypopharyngeal squamous cell carcinoma by suppressing the expression of PTPN11, respectively." (PMID 35957898, 2022). "PTPN11 can be targeted by lncRNA MEG3, thereby suppressing the proliferation and metastasis of renal cell carcinoma." (PMID 35957898, 2022).